TNXB (tenascin XB)
Diseases named in the same sentence as TNXB in open-access papers (continued):
Sharing a sentence is not in itself a finding about the gene and the disease.
cancer (27 papers, 2010 to 2025). A tumor composed of atypical neoplastic, often pleomorphic cells that invade other tissues. "In the cancer context, TNXB expression tends to decrease during cancer progression, while increased expression has been linked to a better prognosis." (PMID 40806327, 2025). "The expression of TNXB is downregulated in some pancreatic cell lines, and it is correlated with a good survival prognosis in pan-cancer." (PMID 37070074, 2023). "In another study using the TCGA database for ECM gene dysregulation in cancer, 58 out of 249 ECM genes were identified as cancer-associated ECM genes and TNXB was found to be the most significantly downregulated among those genes in cancers." (PMID 37007968, 2023). "SLIT3, ABI3BP, MYOCD, PGM5, TNXB and DNAH9 are strongly associated with cancer initiation and progression." (PMID 36451444, 2022). "While 58 of the 249 ECM molecules analyzed were dysregulated in cancers, TNXB was found to be the most significantly downregulated gene overall." (PMID 35785162, 2022). "More recently, TNXB is denoted as one of the triple-evidenced genes, displaying superior predictive ability in cancer diagnosis and prognosis." (PMID 32380793, 2020). "CELSR3, TRPM2, and TRIP13 are over-expressed in all the 13 cancers, TNXB is under-expressed in all the 13 cancers, KCNAB1 is over-expressed in KIRC but under-expressed in the other 12 cancers." (PMID 30729033, 2019). "In our study, we found the aberrant hypomethylation of the TNXB gene, in which constitutive silencing may lead to several cancer outcomes, some of which are evaluated in this study." (PMID 40806327, 2025). "Furthermore, we found that TNXB and SPON1, two ECM proteins, are associated with LNM in GAC patients and play important roles in cancer cell migration." (PMID 36520032, 2023). "In addition, the results also showed that mutated TNXB only existed in the low-expression group of PRAD, while a high expression level of TNXB is correlated with a good survival prognosis in many cancers." (PMID 36578929, 2022). "In agreement with the known downregulation of these genes in cancer, both TNXB and WT1-AS were unmethylated in Mets/Rec samples of SS, indicative of gene loss/downregulation during progression of SS, which has not been previously identified in this tumour type." (PMID 33436720, 2021). "We further explored the mRNA expression of TNXB and SPON1 in other types of cancer from TCGA, similarly comparing the differences in primary tumor samples from patients with or without LNM." (PMID 36520032, 2023). "On the other hand, TNXB is an extracellular matrix (ECM) protein capable of direct interacting with a number of ECM molecules, playing different roles in different type of cancer." (PMID 36520032, 2023). "For examples, TNXB, SPP1 and EMCN have not previously been reported as cancer-related." (PMID 21060876, 2010).
tumor (24 papers, 2010 to 2026). "To validate these findings, we analyzed the TCGA-COAD and TCGA-READ data, and we found similar results, indicating consistent hypomethylation and decreased mRNA expression of the TNXB gene in the tumor area compared to the NAT area (all with p < 0.001)." (PMID 40806327, 2025). "In our exploration of the TNXB gene within our cohort, we observed significant hypomethylation of the TNXB gene in the tumor area compared to the NAT area (p < 0.001)." (PMID 40806327, 2025). "Upon specifically analyzing the total count of DMCs within the TNXB gene, in our cohort, we observed a widespread decrease in methylation levels across the gene in the tumor area compared to the NAT area." (PMID 40806327, 2025). "Our findings highlight TNXB (Tenascin XB) as a novel tumor-suppressor gene in CRC, and further functional approaches are analyzed." (PMID 40806327, 2025). "Genes encoding components of the ECM, including TNXB and MATN2 were identified among downregulated transcripts, together with other participants in tumor progression, including growth factors, such as FIGF and growth factor receptors, such as TGFBR3." (PMID 21611158, 2011). "Among the inactive NBC-hom-related genes, we want to highlight the presence of proteins involved in interactions with the microenvironment, such as ADAM12, ITGA7, SH3PXD2A, and TNXB, since the tumor microenvironment is known to play a key role in MCL growth and therapy resistance." (PMID 41524027, 2026). "We found overall hypomethylation in tumor tissue, primarily focusing on the TNXB gene." (PMID 40806327, 2025). "TNXB is associated with decreased MMP levels and downregulated during tumor progression." (PMID 37430270, 2023). "TNXB induced invasive growth and metastases in tumor cells with stem cell properties." (PMID 36362041, 2022). "Interestingly, TN-X expression is significantly downregulated during tumor progression in most cancers, and a high TNXB expression correlates with a good survival prognosis." (PMID 34206882, 2021). "The downregulation of TNXB in tumors despite hypomethylation may thus reflect the influence of additional regulatory mechanisms, such as histone modifications, altered transcription factor binding, or the tumor microenvironment." (PMID 40806327, 2025). "Notably, TNXB is found to be hypomethylated and downregulated within the tumor area." (PMID 40806327, 2025). "TNXB and brevican (BCAN) are usually heavily glycosylated, remodel the ECM and promote motility, creating a scaffold that facilitates tumor growth, migration, and invasion." (PMID 41440381, 2025). "Together, we confirmed that TNXB and SPON1 were upregulated in GAC tumor tissues from patients with LNM, thus substantiated our proteomic data." (PMID 36520032, 2023). "To seek experimental evidence, we applied western blot analysis and confirmed higher expression of TNXB and SPON1 in GAC tumor tissues from patients with LNM." (PMID 36520032, 2023). "Furthermore, functional analysis reveals that TNXB is epigenetically silenced, and downregulation of TNXB leads to increased cell migration and proliferation in CRC cell lines, suggesting its role as a tumor-suppressor gene." (PMID 40806327, 2025). "In contrast, the increased TNXB expression observed after AZA treatment in vitro supports a role for DNA methylation in its transcriptional regulation, while also underscoring the simplified nature of in vitro systems compared to primary tumor tissue." (PMID 40806327, 2025). "The TNXB expressing C8 mainly resided in NAT with multi‐tumor contributions and might impede the invasion and metastasis of tumor cells." (PMID 38010945, 2024). "Thus, it appears that TNXB and SPON1 displayed certain degree of correlation with the tumor immune microenvironment." (PMID 36520032, 2023).
connective tissue disorder (15 papers, 2016 to 2025). A disease involving the connective tissue. "Among downregulated proteins, we identified tenascin Xb, transforming growth factor β (Tgfb) 2, and Tgfb receptor 1/2, malfunctions of which are linked to connective tissue diseases, such as Ehlers–Danlos and Loeys–Dietz syndromes." (PMID 40869178, 2025). "NR1H3 is involved in lipid metabolic processes, inflammation, and energy homeostasis, while TNXB encodes an extracellular matrix protein and is associated with connective tissue disorders." (PMID 38849516, 2024). "TNXB is responsible for extracellular matrix organization and is associated with connective tissue disorders." (PMID 38849516, 2024). "TNXB deficiency is associated with Classical-like Ehlers–Danlos syndrome (clEDS), which comprises a clinically and genetically heterogeneous group of connective tissue disorders." (PMID 37048094, 2023). "Intriguingly, two of the differentially methylated genes identified in case-control comparisons—NR1H3 (involved in lipid metabolism and inflammation) and TNXB (associated with connective-tissue disorders)—corresponded to those identified by our group." (PMID 32375223, 2020). "Mutations in the TNXB locus are associated with joint hypermobility syndrome, which is a connective tissue disorder characterized by chronic musculoskeletal pain due to joint hyperextensibility." (PMID 33192958, 2020). "TNX functions in extracellular matrix (ECM) maturation and collagen fibrillogenesis, and TNXB null mutations result in the connective tissue disorder Ehlers-Danlos Syndrome." (PMID 30642396, 2019). "We therefore recommend TNXB genotyping for diagnostic purposes for patients with CAH who have 2 or more signs and symptoms of a connective tissue disorder, such as multiple subluxations, generalized hypermobility, hyperextensible skin and hernias." (PMID 31666125, 2019). "TNXB encodes an extracellular matrix glycoprotein, absence of which has been associated with Ehlers–Danlos syndrome, a connective tissue disorder characterized by joint hypermobility that is noted to co-occur with AN." (PMID 32375223, 2020). "TNXB genotyping is recommended for CAH patients who have symptoms of a connective tissue disorder." (PMID 31666125, 2019). "As expected, patients with CAH-X had clinical symptoms of a connective tissue disorder, such as generalized hypermobility, subluxations, chronic arthralgia and hyperextensible skin, than CAH patients without a TNXB mutation." (PMID 31666125, 2019).
infection (2 papers, 2021 to 2022). The state of being infected such as from the introduction of a foreign agent such as serum, vaccine, antigenic substance or organism. "In the 72 h infection group, the mRNA expression was up-regulated and the protein expression was down-regulated in 7 groups, namely the TNXB, NFIA, PROC, SPIN1, NR2C2 nuclear receptor subfamily 2 group C member 2, Carboxypeptidase D and ARHGAP11B." (PMID 36496794, 2022). "In the 72 h infection group, the mRNA expression was up-regulated and the protein expression was down-regulated in seven groups, namely the TNXB, NFIA, PROC, SPIN1, NR2C2 nuclear receptor subfamily 2 group C member 2, Carboxypeptidase D and ARHGAP11B." (PMID 36496794, 2022).
cardiovascular diseases (1 paper, 2025). "Some of these genes are strongly associated with cardiovascular diseases, such as the MUC family, COL18A1, and TNXB." (PMID 40963926, 2025).
TNXB also shares sentences with these, for which no sentence is quoted: myopathies (4 papers); Autoimmunity (2); breast tumors (2); dermatosparaxis (2); Duchenne muscular dystrophy (2); lung adenocarcinoma (2); lymphoma (2); psychiatric disorder (2); acute myeloid leukemia (1); alcohol use disorders (1); allergic rhinitis (1); aneurysmal disease (1); Angina (1); anorexia nervosa (1); Anxiety (1); aortic aneurysm (1); atopic dermatitis (1); benign familial hematuria (1); bipolar disorder (1); bladder cancer (1); cardiac hypertrophy (1); chondrodysplasia (1); Chronic constipation (1); cocaine use disorder (1); colon cancer (1); COVID-19 (1); diabetic neuropathy (1); diabetic retinopathy (1); dilated cardiomyopathy (1); dry eye syndrome (1).
A further 29 diseases each share a sentence with TNXB in 1 paper.